TF (transferrin)
Diseases named in the same sentence as TF in open-access papers (continued):
Sharing a sentence is not in itself a finding about the gene and the disease.
Obesity (continued). "Finally, transferrin saturation values were higher and UIBC was lower in women with obesity-T2D compared to the other two groups, while they were similar in lean women and women with obesity." (PMID 40895225, 2024). "In another study, women with overweight or obesity and central adiposity had higher hepcidin, lower transferrin saturation and impaired absorption of supplemental (but not dietary) iron." (PMID 37029208, 2023). "Obesity is also found to trigger increases in the plasma levels of FVII, thrombin-antithrombin III (TAT) complex, and increased activity in the circulating monocyte TF." (PMID 35406450, 2022). "One-way ANOVA was used to compare the means of different dependent variables between the three groups, namely, group A, group B, and group C, to find out any impact of obesity on the dependent variables, namely, ferritin, Iron, TIBC, hemoglobin (Hb), and transferrin saturation." (PMID 28116148, 2016). "Obesity and insulin are factorsthat raise the iron level in PCOS patients, which iron-oxidativestress governs the function of ovarian tissue,also ferritin and transferrin increases in obese PCOSpatients with inverse correlation between ferritin andthe of the ovaries size." (PMID 37790203, 2023). "Indeed, tissue factor mediates the FVIIa-dependent activation of PAR-2, which was shown to drive DIO and its complications as nonhematopoietic cell TF-FVIIa-PAR-2 signaling promotes obesity." (PMID 35406450, 2022). "In terms of the adipose tissue content, after the eight weeks of fructose diet, the UFP, MF, PFP and TF weights were all significantly higher in the HFD group than in the control group, confirming once again that a high-fructose diet can indeed increase the occurrence of obesity." (PMID 33437204, 2021). "Indeed, the binding regions of EP300, CEBPB, and HDAC2 in the promoters of transferrin (TF), insulin-like growth factor binding protein 1 (IGFBP1) and NQO1, whose expression was increased in obesity and was normalized by CR or RSV, overlap." (PMID 26441656, 2015). "Notably, higher levels of transferrin saturation and lower levels of UIBC in women with obesity-T2D could indicate higher body iron stores in these women than in lean women and women with obesity only." (PMID 40895225, 2024). "In the unadjusted analyses of categorical outcomes, women without obesity taking prescription opioids had higher odds of metabolic syndrome, high waist circumference, low HDL, high triglycerides, high mean corpuscular volume, high serum ferritin, and low serum transferrin saturation." (PMID 37111110, 2023).
trachoma (51 papers, 2010 to 2025). "The measure of facial uncleanliness most associated with clinically active trachoma (i.e., TF and/or TI) was dry ocular discharge (age- and sex-adjusted prevalence ratio [PR] 1.4, 95% CI 1.3–1.6), followed by dirt on the face (PR 1.3, 95% CI 1.1–1.4)." (PMID 38991011, 2024). "All studies examined the association between SEP and active trachoma (TF only, TF and/or TI), usually in young children." (PMID 27171166, 2016). "TF, nucleic acid, and age-specific antibody prevalence collectively indicate that high levels of C. trachomatis transmission among children present a high risk of ocular damage due to trachoma." (PMID 35439248, 2022). "Alternatively, the association between TF and infection may be weakened by temporal change (for example, an ongoing decrease in the prevalence of trachoma throughout the region leading to less frequent exposure to CT, arrested immunity, and prolonged clinical inflammation)." (PMID 31965155, 2021). "The presence of TF and new pannus together was a more specific diagnostic test for Ct infection than either alone but it was much less sensitive; therefore use of this combined clinical sign in a trachoma control programme is likely to underestimate the prevalence of Ct infection." (PMID 26812948, 2016). "Though TF prevalence has been a useful metric for trachoma elimination efforts to date, there are known limitations to its use as a marker of ocular Ct infection, and new challenges have appeared as implementation of the SAFE strategy has continued." (PMID 39406720, 2024). "Trachoma transmission was likely considerably higher when these children were younger and exposed to ocular chlamydia, as evidenced by the higher TF prevalence documented in the 2018 trachoma impact survey." (PMID 39652587, 2024). "Although the serology data from children aged 1–9 years align with the TF prevalence data, the all-age serology data suggest that all three of these North Darfur localities have had a long history of exposure to trachoma." (PMID 38507810, 2024). "We evaluated the prevalence of TF, C. trachomatis as measured by PCR, and serologic markers of trachoma in an area of Niger with low prevalence of TF." (PMID 39652587, 2024). "The current paradigm for clinical TF identification was developed in the milieu of high trachoma prevalence and prior to the era of global adoption of smartphone technology with wireless internet connectivity." (PMID 37023420, 2023). "Given the high prevalence of trachoma in South Sudan12,31 in particular, it is surprising that the prevalence of TF among the refugee population was so low." (PMID 34488539, 2023). "The most common trachoma outcome studied was TF (25 studies), while TT was analysed in seven studies." (PMID 35395003, 2022). "The overall TF prevalence in Kongwa District 2 years post-MDA was 7.1% (95% CI: 5.6%-8.9%) and the age-adjusted TF prevalence was 7.3%, both of which were greater than the established threshold of 5% and suggested that trachoma had re-emerged." (PMID 33861754, 2021). "The prevalence of active trachoma in this age group was 22%, [95%CI, 18–25%], whereas the prevalence of TF was 21%." (PMID 32842993, 2020). "Our data on these additional non-TF markers in this context should stimulate further discussion about their wider role in trachoma surveillance." (PMID 32017971, 2020). "The HDs in Middle and Lower Guinea showed low trachoma prevalence, though there were some clusters in which more than 10% of examined children had TF." (PMID 29889826, 2018). "Ghana has met the active trachoma criterion for elimination of trachoma as a public health problem, a measure based on TF parameters." (PMID 30550537, 2018). "In our TRA in Yunnan Province, only one case of TF was detected out of 450 6–8 years children and the detection rate of active trachoma was only 0.2% in all the nine survey sites." (PMID 29665861, 2018).
trachoma (continued). "The data collected on infection, antibody, scarring and trichiasis prevalence are consistent in their suggestion that trachoma is uncommon in this population despite the moderate TF prevalence." (PMID 29588922, 2018). "To understand the relationship between different measures of transmission intensity (SCR and TF prevalence) we fitted a linear model to the relationship between the SCR for trachoma (λT) (for Pgp3) and TF prevalence for each study site." (PMID 30575720, 2018). "A recent paper analyzed multi-country trachoma survey data which included 2014–2016 survey data from Guinea, found no apparent threshold between community-level water coverage and TF prevalence." (PMID 29889826, 2018). "In this study we present the first attempt to fit a mechanistic epidemiological model of trachoma transmission to bacterial load data, PCR and TF prevalence data across 3 different age groups." (PMID 28182664, 2017). "In 2011, results from the Partnership for the Rapid Elimination of Trachoma (PRET) showed that the overall TF prevalence in four districts was 2.8% (compared to 6.5% at baseline in 2008)." (PMID 28747198, 2017). "In areas of high TF prevalence, IgG serology shows that well over 1/3 of children age 3 and under have been exposed to trachoma antigens, while almost 100% of children age 6 have been exposed." (PMID 24755001, 2014). "Prevalence of active trachoma (TF, TF/TI and TF + TF/TI) before and after treatment among examined children aged between 1 and 10 years." (PMID 21124889, 2010). "In conclusion, while decisions regarding trachoma MDA have usually relied on TF prevalence, which until recently was the only feasible option in the field for assessing trachoma, it is now possible, as illustrated here, to integrate testing for current and previous C. trachomatis infection." (PMID 40920869, 2025). "WHO guidance based on prevalence of TF has been central to the success of the global trachoma elimination program and we show here that a data-driven guideline based on serology could play a complementary role as we approach the trachoma endgame." (PMID 40593530, 2025). "Given the declines in specificity of TF as a marker of conjunctival C. trachomatis infection after A, F and E interventions have commenced, ensuring that these interventions are indicated for trachoma elimination purposes is also important." (PMID 40285493, 2025). "Our estimated Pgp3 seroconversion rate (1.9 per 100 children per year) was also similar to a preliminary operational seroconversion rate threshold of 1.5 per 100 children per year found to correspond to a TF prevalence < 5% based on modeling of data from nine trachoma-endemic populations." (PMID 39406720, 2024). "A random sample of 80 communities was selected from Mayahi and Guidan Roumdji districts, both of which had TF prevalence <20% at their most recent trachoma impact survey in 2018." (PMID 39652587, 2024). "Existing models are over-informed by data from Pacific Island nations, which were early adopters of serological testing as a means to understand the local discordance between high TF prevalences in children and low prevalences of trachomatous trichiasis and trachoma-related blindness in adults." (PMID 33790370, 2021). "However, monitoring the trend in TF prevalence over time provides information about the trajectory of disease and hence trachoma transmission." (PMID 33905484, 2021). "The non-TF markers used in this study help to understand the picture of trachoma in Melanesia in comparison to the neighbouring country of Kiribati, and support suggestions that non-TF markers should be utilised for decision making in Papua New Guinea, Solomon Islands and Vanuatu." (PMID 32017971, 2020). "Similar analyses were performed for TF in order to assess changes in clinically active trachoma." (PMID 30106956, 2018).
trachoma (continued). "There are no reported ethnic group associations with trachoma in Senegal, and as the prevalences of TF and TT were too low to conduct formal risk factor analyses in our study, it was not possible for us to explore any associations in our population." (PMID 28747198, 2017). "Districts in which TF prevalence is between 5 and 10% of 1–9 year olds present a dilemma for trachoma control programmes, as the recommendation to re-survey community by community is considered expensive and impractical, and has not been endorsed by the donation programme." (PMID 23785525, 2013). "The study further suggests that, following the MDAs in its national plan The Gambia has now reached the elimination target for active trachoma: the TF prevalence in 1–9 s may now be below the 5% threshold." (PMID 23785525, 2013). "The lack of an association between being Amplicor positive and TF in The Gambia highlights the poor correlation between the presence of trachoma clinical signs and evidence of C. trachomatis infection in this setting." (PMID 21072224, 2010). "Finally, we identified levels of the SCR that correspond with trachoma program actions, but it remains unknown how current markers of infection in childhood (TF, PCR, serology) relate to future incidence of trichiasis and blindness from trachoma." (PMID 40593530, 2025). "The results from this study, which demonstrated a correlation between higher district-level TF prevalence and scarring severity, suggest that trachoma control programs may also want to focus surveillance efforts on those districts that were formerly the most highly endemic." (PMID 38917786, 2024). "Trachoma is not the only cause of the TF phenotype, and the etiology of follicular conjunctival inflammation may vary by region." (PMID 32970672, 2020). "•Non-TF markers may help to determine need for interventions against active trachoma." (PMID 32017971, 2020). "Overall, 73 EUs (55.7% of all surveyed EUs) had a TF prevalence in 1–9-year-olds <5%, the WHO elimination target for active trachoma." (PMID 36519534, 2023). "All EUs had a TF prevalence in 1–9 year-olds of <5.0%, i.e., below the WHO-defined threshold for elimination of active trachoma, with the lowest having a prevalence of 0% and the highest 2.9%." (PMID 29897902, 2018). "The discrepancy between the two most recent population surveys of clinical trachoma is surprising and it is hard to understand how such a large difference could be explained by simple experimental variation, such as selection of clusters with differing TF prevalence by random chance." (PMID 30440006, 2018). "Although conjunctival swabbing is not part of standard trachoma surveys, infection data would have helped provide more information on the relationship between TF, infection, and serological responses in treatment-naive populations." (PMID 38507810, 2024). "Given that the prevalence of TF was ≤1% in all nine EUs, we infer that the non-indigenous population of Brazil no longer has active trachoma at levels constituting a public health problem." (PMID 34711133, 2023). "The lack of a difference in scarring progression rates despite TF prevalence dramatically dropping in this district suggests that the drivers of scarring progression are likely not related to on-going trachoma transmission in this district." (PMID 34797827, 2021). "Where trachoma was endemic prior to mass drug administration (MDA), the antibody seroprevalence was typically 2–3 times that of TF prevalence, likely representing greater longevity of antibody-secreting plasma cells than the follicles that characterize TF." (PMID 32970672, 2020). "The low TF prevalence in the Casamance region was unexpected since no specific trachoma control efforts have been implemented there, unlike in other regions of Senegal or the neighbouring countries of The Gambia and Mali." (PMID 28747198, 2017).
trachoma (continued). "Reactivity to Pgp3 was higher in children with active trachoma than in those with neither TF nor TI, and significantly higher in those with conjunctival Ct infection than in those without (logistic regression p<0.0001)." (PMID 28898240, 2017). "The difference in TF prevalence between the present data and the 2012 PBPS could be due to poor consensus between graders, seasonal variation in trachoma prevalence or an artefact of the cross-sectional study designs." (PMID 27404379, 2016). "The same proportion of positive specimens was found by GeneXpert and Amplicor in children with TF, 39% and slightly more with GeneXpert in children with TI and in children without signs of trachoma." (PMID 23861986, 2013). "Of note, field cases of trachoma were not overrepresented among the ungradable images in our study, so presumably the proportion of cases with TF was not affected, but that may not always be the case." (PMID 34748543, 2021). "In the context of trachoma elimination, a lack of specificity of TF as an indicator will make it increasingly difficult to ensure that EUs are correctly categorised as endemic or not and that valuable resources are not wasted by unnecessarily prolonging interventions." (PMID 30550537, 2018). "Thus, it is possible that a TF prevalence decrease due to secular trend, i.e. in the absence of trachoma control programmes, may have occurred." (PMID 28747198, 2017). "Accordingly, the TF prevalence among children in Kotom was <5% despite the locality having similar WASH indices as the other two localities and no history of trachoma interventions." (PMID 38507810, 2024). "More investigation is needed to understand why Kotom has a current TF prevalence below threshold in the absence of MDA or other interventions, especially considering that the serology and TT data suggest a history of trachoma in this locality." (PMID 38507810, 2024). "Here, the prevalence of TF in 1–9-year-olds was <5% in all 11 EUs studied, suggesting antibiotic MDA is not warranted in these populations for trachoma elimination purposes." (PMID 34488539, 2023).